KCTD19 (potassium channel tetramerization domain containing 19)
Description:
Transcription regulator which is essential for male fertility and for the completion of meiotic prophase in spermatocytes. Regulates progression of the pachytene stage of meiotic prophase and promotes the transcriptional activation activity ZNF541. Required for the organization of chromosomes during metaphase I.
Synonyms: FLJ40162
Tractability: No criterion of Open Targets' tractability assessment is met for any kind of drug.
Gene: Protein-coding gene on chromosome 16 (67,289,428 to 67,326,760, reverse strand). Ensembl gene ENSG00000168676.
Subcellular location: Nucleus
Gene Ontology:
Molecular function: protein binding; identical protein binding
Biological process: male meiotic nuclear division; protein homooligomerization
Cellular component: nucleus
Genetic constraint (gnomAD): Loss-of-function variants: 56 observed, 94.6 expected, observed/expected ratio (o/e) 0.59, 90% interval 0.48 to 0.74. The upper end of that interval is the gene's LOEUF score, 0.74, which puts it in group 3 of 6, group 1 being the genes least tolerant of losing a copy. Missense variants: 937 observed, 1,136.4 expected, observed/expected ratio (o/e) 0.82, 90% interval 0.78 to 0.87. Synonymous variants: 420 observed, 453.97 expected, observed/expected ratio (o/e) 0.93, 90% interval 0.85 to 1.
Homologues: Orthologues: macaque KCTD19 (97% identical), rabbit KCTD19 (93% identical), pig KCTD19 (91% identical), dog KCTD19 (91% identical), rat Kctd19 (89% identical), mouse Kctd19 (89% identical), guinea pig KCTD19 (88% identical), chimpanzee KCTD19 (82% identical), Drosophila melanogaster twz (6% identical), Caenorhabditis elegans F32B4.5 (4% identical). Paralogues in human: KCTD1 (10% identical), KCTD8 (9% identical), KCTD15 (9% identical), KCTD16 (8% identical), KCTD12 (8% identical), KCTD21 (7% identical), KCTD18 (7% identical), KCTD11 (6% identical), KCTD7 (6% identical), KCTD6 (6% identical), KCTD14 (6% identical), KCTD4 (5% identical), and 1 more.
Diseases named in the same sentence as KCTD19 in open-access papers:
KCTD19 is named in the same sentence as 5 diseases in open-access papers, as found by Europe PMC text mining. Sharing a sentence is not in itself a finding about the gene and the disease. The quoted sentences say what the papers report.
male infertility (4 papers, 2021 to 2023). The inability of the male to effect fertilization of an ovum after a specified period of unprotected intercourse. "Considering the available evidence presented previously and the infertile phenotype of Kctd19 knockout mice, we propose that these KCTD19 variants are the most likely pathogenic variants for male infertility in these individuals." (PMID 37485353, 2023). "Our study provides genetic and functional evidence that loss-of-function variants in KCTD19 cause autosomal recessive spermatogenic failure and male infertility, extending the current phenotypic spectrum associated with KCTD gene variants." (PMID 37485353, 2023). "Further research studies involving a larger cohort of infertile men are required to accurately determine the clinical significance and implications of KCTD19 variants in male infertility." (PMID 37485353, 2023). "In conclusion, our study based on NOA affected individuals and mutant mouse models demonstrate that homozygous loss-of-function variants in KCTD19 cause meiotic arrest at MMI and male infertility in mice and humans." (PMID 37485353, 2023). "KCTD19 can be used as a genetic screening marker for male infertility and to assess the chances of successful sperm retrieval prior to testicular biopsy." (PMID 37485353, 2023). "Therefore, we regarded this Kctd19-ΔBTB line as equivalent to Kctd19del/del line, in that both lines result in male infertility, to corroborate that Kctd19 is essential for male fertility." (PMID 33961623, 2021). "We performed Cr‐CEST by using 7T MRI on wild‐type C57B6/J mice and several types of male infertility models such as Sertoli‐cell only (SCO) (Kitw/Kitwv), maturation arrest (MA) (Zfp541 knockout mouse and Kctd19 knockout mouse), and teratozoospermia (Tbc1d21 knockout mouse)." (PMID 36845001, 2023).
Azoospermia (3 papers, 2021 to 2023). Absence of any measurable level of sperm,whereby spermatozoa cannot be observed even after centrifugation of the semen pellet. "In this study, we generated Kctd19 KO mice using the CRISPR/Cas9 system and revealed that Kctd19 deficiency causes azoospermia due to incomplete meiosis." (PMID 33961623, 2021). "Although KCTD19 and LRRC36 genes are mainly expressed in the testis and could not be directly associated with POI phenotype, KCTD19 knockout mice produced spermatocytes that failed to complete meiosis, leading to azoospermia, indicating its role in meiosis and, putatively, gametogenesis in general." (PMID 37202802, 2023).
infertile (1 paper, 2023). "Next, we screened infertile men born in consanguineous families from the Pakistani population and identified homozygous nonsense variants in KCTD19 that recessively co-segregated with infertility within the family." (PMID 37485353, 2023). "The third KCTD19 variant (p.Gln669∗) was found in one of 50 Pakistani consanguineous families with at least two infertile siblings in each." (PMID 37485353, 2023). "In this study, we have successfully identified pathogenic variants of KCTD19 in two infertile Chinese men and in a Pakistani family consisting of three infertile brothers." (PMID 37485353, 2023).
Obstructive azoospermia (1 paper, 2023). Absence of any measurable level of sperm in his semen, resulting from post-testicular obstruction or retrograde ejaculation. "To examine the detailed meiotic defects of affected individuals carrying homozygous KCTD19 variants, we performed hematoxylin and eosin (H&E) staining on testicular sections from P7864, P2034 and a man diagnosed with obstructive azoospermia (OA), serving as the control." (PMID 37485353, 2023).
KCTD19 also shares sentences with these, for which no sentence is quoted: teratozoospermia (1 paper).